TRBV6-5 (T cell receptor beta variable 6-5)
Description:
V region of the variable domain of T cell receptor (TR) beta chain that participates in the antigen recognition. Alpha-beta T cell receptors are antigen specific receptors which are essential to the immune response and are present on the cell surface of T lymphocytes. Recognize peptide-major histocompatibility (MH) (pMH) complexes that are displayed by antigen presenting cells (APC), a prerequisite for efficient T cell adaptive immunity against pathogens. Binding of alpha-beta TR to pMH complex initiates TR-CD3 clustering on the cell surface and intracellular activation of LCK that phosphorylates the ITAM motifs of CD3G, CD3D, CD3E and CD247 enabling the recruitment of ZAP70. In turn ZAP70 phosphorylates LAT, which recruits numerous signaling molecules to form the LAT signalosome. The LAT signalosome propagates signal branching to three major signaling pathways, the calcium, the mitogen-activated protein kinase (MAPK) kinase and the nuclear factor NF-kappa-B (NF-kB) pathways, leading to the mobilization of transcription factors that are critical for gene expression and essential for T cell growth and differentiation. The T cell repertoire is generated in the thymus, by V-(D)-J rearrangement. This repertoire is then shaped by intrathymic selection events to generate a peripheral T cell pool of self-MH restricted, non-autoaggressive T cells. Post-thymic interaction of alpha-beta TR with the pMH complexes shapes TR structural and functional avidity.
Synonyms: TRBV65; TCRBV13S1; TCRBV6S5
Gene: T-cell receptor variable (V) gene on chromosome 7 (142,450,947 to 142,451,448, forward strand). Ensembl gene ENSG00000211721.
Subcellular location: Cell membrane
Gene Ontology:
Biological process: cell surface receptor signaling pathway
Cellular component: plasma membrane
Homologues: Paralogues in human: TRBV6-6 (89% identical), TRBV6-8 (87% identical), TRBV6-7 (85% identical), TRBV6-2 (83% identical), TRBV6-1 (82% identical), TRBV6-4 (70% identical), TRBV10-2 (61% identical), TRBV10-3 (61% identical), TRBV10-1 (59% identical), TRBV27 (56% identical), TRBV25-1 (51% identical), TRBV19 (50% identical), and 39 more.
Diseases named in the same sentence as TRBV6-5 in open-access papers:
TRBV6-5 is named in the same sentence as 2 diseases in open-access papers, as found by Europe PMC text mining. Sharing a sentence is not in itself a finding about the gene and the disease. The quoted sentences say what the papers report.
infection (2 papers, 2024). The state of being infected such as from the introduction of a foreign agent such as serum, vaccine, antigenic substance or organism. "TRBV6-5 and BCL11B are primarily implicated in the immune response post-infection; PTGDS, EGR3, and CXCR5 modulate the host’s inflammatory response." (PMID 39591343, 2024). "The DEG analysis showed that LAIR2, CD7, KLRB1, TYROBP, TRAV19, TRAV21, and TRBV6-5 were upregulated in group E VS group B both breakthrough infection by BA.5.2." (PMID 39835127, 2024).
bacterial infection (1 paper, 2023). "PRP also upregulated the genes involved in the beta chain of the T cell receptor (TRBV3‐1, TRBV6‐5, TRBV7‐2, TRBV27, TRBC2, and TRBJ2‐3), which is responsible for antigen recognition and activation of cellular immunity during bacterial infection." (PMID 36704119, 2023).